PLPP6 (phospholipid phosphatase 6)
Description:
Magnesium-independent polyisoprenoid diphosphatase that catalyzes the sequential dephosphorylation of presqualene, farnesyl, geranyl and geranylgeranyl diphosphates. Functions in the innate immune response through the dephosphorylation of presqualene diphosphate which acts as a potent inhibitor of the signaling pathways contributing to polymorphonuclear neutrophils activation. May regulate the biosynthesis of cholesterol and related sterols by dephosphorylating presqualene and farnesyl diphosphate, two key intermediates in this biosynthetic pathway. May also play a role in protein prenylation by acting on farnesyl diphosphate and its derivative geranylgeranyl diphosphate, two precursors for the addition of isoprenoid anchors to membrane proteins. Has a lower activity towards phosphatidic acid (PA), but through phosphatidic acid dephosphorylation may participate in the biosynthesis of phospholipids and triacylglycerols. May also act on ceramide-1-P, lysophosphatidic acid (LPA) and sphing-4-enine 1-phosphate/sphingosine-1-phosphate.
Synonyms: LPRP-B; PDP1; PPAPDC2; FLJ90191; FLJ46512; PA-PSP; PSDP; bA6J24.6
Tractability: Antibody: its Gene Ontology location is reachable by antibodies, with high confidence; UniProt predicts a signal peptide or a membrane-spanning region. PROTAC: its protein half-life has been measured.
Gene: Protein-coding gene on chromosome 9 (4,662,294 to 4,665,258, forward strand). Ensembl gene ENSG00000205808.
Subcellular location: Endoplasmic reticulum membrane; Nucleus envelope; Nucleus inner membrane
Subcellular location (Human Protein Atlas): Nucleoplasm; Vesicles; Cytosol
Pathways (Reactome):
Metabolism: Lanosterol biosynthesis
Gene Ontology:
Molecular function: farnesyl diphosphatase activity; isoprenoid diphosphate phosphatase activity; lipid phosphatase activity; lysophosphatidic acid phosphatase activity; phosphatidate phosphatase activity; protein binding; sphingosine-1-phosphate phosphatase activity; hydrolase activity
Biological process: farnesyl diphosphate catabolic process; geranyl diphosphate metabolic process; geranylgeranyl diphosphate catabolic process; isoprenoid metabolic process; phospholipid dephosphorylation; positive regulation of neutrophil activation; protein prenylation; cholesterol biosynthetic process; cholesterol homeostasis
Cellular component: endoplasmic reticulum membrane; nuclear envelope; nuclear membrane; membrane; plasma membrane; nuclear inner membrane
Genetic constraint (gnomAD): Loss-of-function variants: 16 observed, 13.32 expected, observed/expected ratio (o/e) 1.2, 90% interval 0.81 to 1.76. The synonymous counts are far from expectation, so gnomAD's model fits this gene poorly and the ratio says little. Missense variants: 512 observed, 361.59 expected, observed/expected ratio (o/e) 1.42, 90% interval 1.32 to 1.52. Synonymous variants: 226 observed, 167.81 expected, observed/expected ratio (o/e) 1.35, 90% interval 1.21 to 1.5.
Homologues: Orthologues: chimpanzee PLPP6 (99% identical), macaque PLPP6 (98% identical), pig PLPP6 (88% identical), rabbit PLPP6 (88% identical), mouse Plpp6 (87% identical), rat Plpp6 (87% identical), guinea pig PLPP6 (86% identical), dog PLPP6 (74% identical), tropical clawed frog plpp6 (62% identical), zebrafish plpp6 (61% identical), Drosophila melanogaster CG31717 (24% identical), Caenorhabditis elegans T13C5.6 (21% identical). Paralogues in human: PLPP7 (46% identical), SGPP2 (16% identical), SGPP1 (15% identical).
Diseases named in the same sentence as PLPP6 in open-access papers:
PLPP6 is named in the same sentence as 7 diseases in open-access papers, as found by Europe PMC text mining. Sharing a sentence is not in itself a finding about the gene and the disease. The quoted sentences say what the papers report.
tumor (2 papers, 2021 to 2025). "PLPP3, PLPP4, and PLPP6 were differentially elevated in some cancers, particularly PLPP4 showed “with” and “without” expression in cancer or tumor tissues (T) compared to the respective adjacent normal tissues (N)." (PMID 34917513, 2021).
PLPP6 also shares sentences with these, for which no sentence is quoted: breast carcinoma (1 paper); cancer (1); infection (1); lung adenocarcinoma (1); lung carcinoma (1); lung squamous cell carcinoma (1).